ENSG00000280434 (novel transcript, sense overlapping PARVB)
Gene: Long non-coding RNA gene on chromosome 22 (44,139,365 to 44,153,626, forward strand). Ensembl gene ENSG00000280434.
Gene Ontology:
Molecular function: triplet codon-amino acid adaptor activity
Biological process: translation